LGALS9 (galectin 9)
Diseases named in the same sentence as LGALS9 in open-access papers (continued):
Sharing a sentence is not in itself a finding about the gene and the disease.
tumor (continued). "Expression of the ‘Vessel maturation’ marker LGALS9 was correlated with tumour positive lymph nodes, suggesting it might play a role in metastasis to the lymph nodes." (PMID 25889974, 2015). "It warrants further explore whether TIM-3 receives an inhibitory signal from an unidentified molecule other than galectin-9 on tumor cells where blockade of this interaction by anti-TIM-3 mAb elicits an immunostimulatory effect." (PMID 24044888, 2013). "Together, our results suggest that the Tim-3-galectin-9 pathway may contribute to the suppressive tumor microenvironment in human cancer by promoting regulatory T cells." (PMID 23526963, 2013). "Future aims will be to investigate whether galectin-9 abundance in tissue sections is predictive of responses to various tumor modalities, especially adoptive immunotherapy." (PMID 22805533, 2012). "Indeed, recent works have shown the presence of tumor exosomes carrying galectin-9 in the blood of NPC patients." (PMID 22805533, 2012). "PD-1 ligand B7-H1 and TIM-3 ligands such as galectin-9 and apoptotic cells within the tumor tissue might be important for maintaining the number and function of TIM-3+PD-1+ Tregs." (PMID 22363469, 2012). "Secreted galectin-9 from tumor cells or KC may explain the increase in Tregs and decrease in CD8 T cells seen in the peritumor region of HCC." (PMID 20209097, 2010). "We discovered that tumor-derived exosome carrying 3′tiRNA-AlaCGC target fibroblasts, inducing a senescence-associated secretory phenotype (SASP) and activating the TGF-β/Smad3 pathway to increase Galectin-9 secretion; both SASP and Galectin-9 are known to induce CD8+T cell exhaustion." (PMID 40855047, 2025). "Additionally, he investigates recurrence risk assessment in SCLC, identifying Galectin-9 (Gal-9) in TME and (tumor-infiltrating lymphocytes)TILs as a promising predictive immune biomarker, with Gal-9 expression levels correlating significantly with the immune risk score." (PMID 41293265, 2025). "However, we did not detect differences in the mRNA levels of these factors between tumors with and without mitofusin 1, maybe because other immune cells present in the tumor can also express Ccl5 and Lgals9." (PMID 38195762, 2024). "Moreover, recent studies have shown that IFN-γ could stimulate galectin-9 expression in tumour and immune cells via EZH2." (PMID 38166741, 2024). "High TIM3/Galectin-9 enrichment is related to immunosuppressive TME, inferior prognosis, and severe clinical manifestations, which may be caused by the impairment of the anti-tumor function of exhausted CD8+TILs." (PMID 38369502, 2024). "In a mouse model of PDAC, blockade of galectin-9 function could effectively retard tumor progression and prolonged survival by inducing maturation and expansion of macrophages and dendritic cells, and modulating the immune response of NK and tumor-associated CD8+ T cells (141–, 143)." (PMID 36873388, 2023). "In addition, the tumor microenvironment efficiently upregulates the expression of galectin-9 on mast cells, which can suppress CD8+ T cells in antitumor immunity in a galectin-9-dependent manner in TC, suggesting a novel mechanism of tumor immune escape during TC progression." (PMID 37042867, 2023). "However, the mechanism of galectin-9 and apoptosis induction in gastrointestinal cancers and the detailed mechanisms involved in tumor growth inhibition remain unknown." (PMID 37047155, 2023). "Therefore, the combination of immune checkpoint inhibitor therapy and inhibition of LGALS9, along with fatty acid metabolic pathways, could significantly enhance the success of tumor immunotherapy." (PMID 37686016, 2023). "Thus, LGALS9–HAVCR2 is used by tumor-infiltrating pDCs to exert immunosuppressive functions." (PMID 37817484, 2023). "Besides, the tumor cells may inhibit the function of NK cells by the expression of LGALS9 in NK-NPC." (PMID 37098551, 2023).
tumor (continued). "Interestingly, we found that the level of the immunosuppressive molecule galectin-9 in tumor-associated mast cells was higher than that in non-tumor mast cells." (PMID 37042867, 2023). "We speculated that, tumor cells can suppress T-cell and NK cell function by secreting LGALS9." (PMID 37098551, 2023). "However, other immunosuppressive molecules expressed on tumor cells such as PD-L1, Galectin-9 and Siglec-15 may also be retained on cellular vesicles and inhibit the function of tumor-infiltrating lymphocytes." (PMID 35874757, 2022). "Indeed, they also reported that TGF-β may regulate galectin-9 (Gal-9) expression by the Smad3 pathway in tumor cells." (PMID 35432324, 2022). "Therefore, tumor-derived exosomal Galectin-9 acts as a major regulator of tumor progression by inhibiting DCs maturation and antigen presentation to activate cytotoxic T-cells in the CSF and that loss of this inhibitory effect can lead to durable systemic antitumor immunity." (PMID 34078376, 2021). "Indeed, tumor galectin-9 also interacts with VISTA in T lymphocytes." (PMID 34572756, 2021). "Conversely, when galectin-9 acts directly on tumor cells, it may inhibit tumor growth." (PMID 35008740, 2021). "Thus, the low expression of LGALS9 in tumor tissues from patients with SCC might weakly interact with TIM-3 expressed on CIKs and finally facilitate CIK treatment efficacy in patients with SCC." (PMID 34459571, 2021). "In addition, tumoral HHLA2 expression and stromal levels of PD-L1, B7H3 and Galectin-9 could predict tumor features, the immune response in the microenvironment and patient outcomes." (PMID 35145510, 2021). "Therefore, exosomal LGALS9 promotes tumor growth by suppressing the immune system." (PMID 33093453, 2020). "Besides a direct modulating effect of the antitumoral treatment on galectin-9 expression, the general reduction of tumor cells may contribute to this observation." (PMID 32055023, 2020). "However, no studies have focus on whether LGALS9 in GBM exosomes can induce inhibitory immunity in the tumor microenvironment, so we focused our attention on LGALS9." (PMID 33093453, 2020). "T-cell immunoglobulin and mucin-domain containing-3 (Tim-3) negatively regulates Th1 immunity, once Tim-3 binds to its ligand galectin-9 could inhibit Th1 and Th17 responses by hampering their expansion, its mediating immune exhaustion in tumor microenvironment." (PMID 32699524, 2020). "Hence, the function of Galectin-3 and Galectin-9 and their correlation with tumor prognosis remain largely unknown." (PMID 32995093, 2020). "Interestingly, high levels of Tim-3 are known to be expressed by solid tumor-infiltrating lymphocytes, which could be used by tumor-derived galectin-9 to kill them." (PMID 31354733, 2019). "However, this tumor-associated galectin-9 is unlikely to be secreted since blood plasma levels of galectin-9 are lower than in healthy donors." (PMID 31354733, 2019). "In summary, the patients with high Galectin-9 expression in recurrent NPC was associated with a higher percentage of Tim-3+ lymphocytes and a more immunocompromised status (a lower percentage of CD8+ and higher percentage of Foxp3+ lymphocytes) in the tumour microenvironment." (PMID 28871094, 2017). "Thus, the Tim-3-galectin-9 pathway could regulate homeostasis of the immune response by balancing the Treg and Teff responses in the tumor microenvironment." (PMID 23526963, 2013). "Tumor cells utilize various mechanisms to evade immune system surveillance, including the expression of checkpoint proteins such as PD-L1, CTLA-4, Galectin-9, and PVR." (PMID 41550509, 2026). "Additional interactions with CTLA4, LAG3, LGALS9, and CD4 placed PD-1 at the center of a dynamic immunoregulatory network critical for tumor immune evasion." (PMID 40927719, 2025). "Analyses of bulk RNA-seq of human ccRCC revealed that PDCD1LG2 and CD80 expression were upregulated in ccRCC tumours compared to normal kidney, as was expression of LGALS3, LGALS9, SELL and CD276." (PMID 40473819, 2025).
tumor (continued). "Galectin-9 (LGALS9) regulates immune homeostasis and tumor cell survival through its interaction with its receptor TIM-346." (PMID 41184358, 2025). "UMAP plots of LGALS9 and CD44 expression in both tumor and immune cells were visualized, confirming the importance of this signaling axis." (PMID 40933995, 2025). "This enhancement is mediated through the activation of signaling axes such as TGF-β, VEGFA, and LGALS9-HAVCR2, thereby facilitating immune evasion and promoting tumor angiogenesis." (PMID 41252877, 2025). "The results of interactome analyses led us to target galectin-9 in a CLL mouse model, which resulted in improved T-cell function and an attenuated tumor development." (PMID 40775219, 2025). "LGALS9, a TIM-3 ligand, plays a crucial role in immune suppression within the tumor microenvironment, indicating its potential as a therapeutic target for high-risk patients." (PMID 40243888, 2025). "Of interest, galectin-9 levels are increased in serum of patients with CLL40–42, and binding of galectin-9 to TIM3 induces T-cell death and thus contributes to tumor immune escape." (PMID 40775219, 2025). "Central to the progression and immune evasion of PDAC is the tumor (immune) microenvironment (TIME), where immune checkpoint proteins such as galectin-9 (Gal-9) play pivotal roles." (PMID 39958335, 2025). "After different levels of clustering, cell types of interest were identified, and the expression of LGALS9 and HAVCR2 was retrieved for each cell type and different compartments (blood, paratumor, and tumor tissue)." (PMID 41323263, 2025). "PD-L1 and TIM3 ligands (LGALS9, PTDSS1, CEACAM1, and HMGB1) were identified on macrophages, DCs, and tumor cells." (PMID 40027748, 2025). "For example, galectin-9 on glioblastoma-derived EVs binds TIM-3 receptor on DCs, which inhibits DC antigen presentation and suppresses T cell-mediated anti-tumor immune responses." (PMID 40908470, 2025). "The results showed a significant correlation between CHST11 and certain tumor immunostimulators (CD28, IL2RA, and TNFSF13B), tumor immunoinhibitors (CD96 and LGALS9), and MHC proteins (HLA-DRA and HLA-DMB)." (PMID 38565604, 2024). "For instance, Galectin-9 is a TIM-3 ligand that acts as a negative regulator and can induce cell death in the tumor microenvironment." (PMID 38338674, 2024). "We also observed intensive interactions of CD274-PDCD1, PDCD1LG2-PDCD1, and LGALS9-HAVCR2 between iCAFs and tumor-infiltrating T cells, which are well-characterized immune checkpoint axes, suggesting their immunosuppressive capability on T cells." (PMID 38182569, 2024). "To explore the correlation between Plek2 knockdown and immunomodulatory molecules, we collected tumor tissues from C57BL/6 mice bearing tumors and extracted RNA for RT-PCR analysis of Cd276, Cd274, and Lgals9 expression." (PMID 39546161, 2024). "The results showed that CD200, CD80 and TNFRSF14 were the highest in tumor tissues, CD274 (PDL1), CD86, LGALS9, NECTIN2, PDL2, PVR were lower than those in adjacent tissues but higher than those in normal tissues, and FGL1 was the lowest in tumor tissues." (PMID 39120585, 2024). "Galectin-9 is also involved in the pathogenesis of CLL by blocking the host’s anti-tumor immune responses and making changes in tumor microenvironments." (PMID 37946029, 2024). "Accordingly, we demonstrated herein that NExT are naturally functionalized with diverse receptors (PD1, LAG3, TIM3) that can interact with their corresponding ligands (e.g., PDL1, Galectin-3, FGL-1, MHCII, Galectin-9, HMGB1, Ceacam-1) within the tumor." (PMID 38730475, 2024). "Galectin-9 and several of the identified SASP components had been reported to play immunosuppressive roles in the tumor microenvironment." (PMID 38195762, 2024). "Galectin-9/TIM-3 signaling blockade with anti-TIM-3 antibody reduces apoptosis and, in addition, inhibits tumor growth in mice." (PMID 38891037, 2024).
tumor (continued). "This analysis led to the identification of genes generally associated with cancer cells (MUC1, LGALS3, UGDH, TSTA3, and GALE) or the stromal compartment (LGALS1, PSAP, LGALS9, IDS, and MGAT1) in most of the tumor types analyzed." (PMID 38384845, 2024). "Galectin-9 (Gal-9) is an immune checkpoint protein that promotes TEX and modulates the tumor microenvironment." (PMID 39717767, 2024). "Compared with the a-PD-1–treated tumor, the tumor treated with TGF-β-TRAP+a-PD-1 also demonstrated enhanced LGALS9/TIM3 signaling." (PMID 39298276, 2024). "Another study found that combining a galectin-9 inhibitor with AZD1930, an ATM inhibitor, led to decreased tumor growth and significantly longer survival for mouse models." (PMID 38927753, 2024). "Consistently, comparisons of LGALS9 and FOXP3 mRNA levels, which represent tumor galectin‐9 and Tregs, respectively, in the TCGA LUAD dataset also revealed a positive correlation." (PMID 38528665, 2024). "Inhibition of different parts of this axis by α-lactose or Tim-3 antibody or LGALS9-targeted shRNAs can regulate TAM polarization and inhibit angiogenesis and tumor proliferation." (PMID 37598273, 2023). "This is further supported by the increased expression of the anti-tumor immunity genes PDL1, CD155 (PVR), CEACAM1, LGALS9, and IDO1, all of which antagonize T cell responses via their interaction with inhibitory receptors." (PMID 36680216, 2023). "A remarkable point about Galectin-9, TIM-3, and VISTA is that they are expressed on both T-cells and tumor cells." (PMID 37970435, 2023). "The interaction pairs via SPP1, RARRES2, NECTIN3, LGALS9, and LAMB1 showed increased signaling in the autophagy-high tumor cells, while SEMA3C, PTN, ICAM1, GAS6, and CSF1 showed decreased signaling compared with those in the autophagy-low tumor cells." (PMID 36830707, 2023). "Meanwhile, overexpression of TIM-3 on dendritic cells in the tumor area suppresses innate immune responses through recognition of nucleic acids by TLR receptors and cytosolic sensors in a galectin-9-independent mechanism." (PMID 37567938, 2023). "EBVaGCs also displayed a higher expression of anti-tumor immunity factors (PDL1, CD155, CEACAM1, galectin-9, and IDO1)." (PMID 36680216, 2023). "TIM-3 interacts with galectin-9 (MIM: 601879) expressed by regulatory T cells (and certain tumor cells) to induce CD8+ T cell apoptosis." (PMID 37339630, 2023). "Tumor cells have been shown to escape killing by expressing surface immune suppressor molecules, and CD122, Galectin-9, and PD-L1 are commonly used to impair NK and T-lymphocyte-mediated attacks." (PMID 37341216, 2023). "Recently, LGALS9, which is highly expressed by PDAC tumor cells, has emerged as a promising new biomarker in PDAC and a target for immunotherapy." (PMID 38098486, 2023). "A recent study suggested that the co-inhibition of LGALS9 and CD274 (PDL-1) resulted with a more effective tumor growth inhibition in PDAC19." (PMID 37945567, 2023). "We also observed increased expression levels of immune‐related genes, such as SLAMF7, TNFSF8, BTN3A1, CD2, LGALS9, PRF1, and MX2, in tumor samples from the MT group of the Local‐SCLC cohort." (PMID 38125769, 2023). "Through Tim-3/galectin-9 (Gal-9) and CD40L/CD40 axes, tumor-induced senescent T cells interact with Mo/Ma, participating in the latter’s canonical activation and thus indirectly facilitating angiogenesis." (PMID 37046588, 2023). "To see if LGALS9, HBEGF, and GRN mediate tumor-macrophage interactions and contribute to PDAC progression, we performed in vitro experimental studies for validation." (PMID 36864399, 2023). "Gene expression levels of ANXA1-FPR3, NECTIN2-TIGIT, CXCL8-NR3C1, LGALS9-HAVCR2, C5AR1-RPS19, and SPP1-PTGER4 pairs were higher in sender and receiver cells derived from tumor tissue compared with normal tissue." (PMID 38002057, 2023). "Galectin-9, TIM-3, and VISTA are expressed in both tumor cells and T-cells, where they can act as both receptors and ligands." (PMID 37970435, 2023).
tumor (continued). "Galectin-9 (Gal-9), initially identified as a ligand for TIM-3 to induce T cell death, acts as an immunosuppressive regulator in the tumor microenvironment (TME) but its potential as a therapeutic target remains largely elusive." (PMID 36778120, 2023). "Since TIM-3 is highly expressed on CD8+ T and FoxP3 Treg cells, both of which assume key roles in the formation of tumor immunosuppression, blocking the TIM-3/galectin-9 pathway is of great interest." (PMID 36428567, 2022). "There are four known ligands for TIM-3: the first recognized and most widely studied is galectin-9 (gal-9), which induces the apoptosis of TH1 cells, playing a crucial role in tumor cell immune evasion." (PMID 36612249, 2022). "In this review, we present the proliferative role of 15 immune checkpoints, including PD1, PD-L1, FGL1, CD155, CD47, SIRPα, CD276, IDO1, SIGLEC-15, TIM3, Galectin-9, CD70, CD27, 4-1BBL, and HVEM, in tumor progression." (PMID 36358792, 2022). "All three wildtype target tumor cell lines used in this study (RMA-S, B16 and YAC-1) showed an expression of Gal-9, and Lgals9-/- YAC-1 showed complete loss of Gal-9 expression upon evaluation by western blotting." (PMID 36232695, 2022). "TDE contains tumor-specific antigens, tumor-related proteins, and immunosuppressive molecules, such as FasL, CD95L, TRAIL, and galectin-9, promoting T cell apoptosis." (PMID 35565418, 2022). "Sabatolimab, an inhibitor of T-cell immunoglobulin and mucin domain-containing protein 3 (TIM3), which disrupts its binding to galectin-9, has shown promising results in AML/MDS, enhancing the effector functions of lymphocytes and triggering tumor cell death." (PMID 35886899, 2022). "In contrast, some inhibitory ICR/ICL pairs such as CD24-SIGLEC10 and LGALS9-HAVCR2 were frequently observed between myeloid cells, master cells, B cells and tumor cells." (PMID 36172359, 2022). "The results indicated that iEXO-OXA promoted the polarization of M2 phenotype to M1 phenotype upon disrupting the combination of galectin-9 and dectin 1, and TME was reprogrammed, increasing anti-tumor immunity for pancreatic cancer." (PMID 36733388, 2022). "The results showed that CD68 expression positively correlated with the expression of LAIR1, HAVCR2, LGALS9, and PD-1 (PDCD1) in most of the 33 tumor types." (PMID 35550532, 2022). "Currently, only PD1/PD-L1, CD47/SIRPα, TIM3/Galectin-9, and CD70/CD27 checkpoints have been shown to interact with each other to regulate tumor proliferation in pairs." (PMID 36358792, 2022). "With regard to ICs, the expression of HAVCR (p = 0.782), LGALS9 (p = 0.179) and NT5E (p = 0.015) were higher in tumor tissue in comparison with para-tumor." (PMID 35163489, 2022). "Galectin-9 expression in cancer cells lacking functional TLR4 could still be triggered by HMGB1 indirectly via induction of TGF-β expression in TLR4-positive myeloid cells (e.g. tumour-associated macrophages) present in the tumour microenvironment." (PMID 34234778, 2021). "Galectin 9 is expressed in multiple cell types, with CEACAM1 also being highly expressed by some tumor cells." (PMID 34638305, 2021). "NK–tumor interactions included HLA-C/KIR2DL4, HLA-E/CD94 (KLD1), TIM3 (HAVCR2)/Galectin-9, CD96-PVR/Nectin1 and TIGIT-PVR/Nectin2." (PMID 33671917, 2021). "We then analyzed the coexpression of the QIF markers in the tumor compartment, as well as the coexpression of B7H3, IDO-1 and Galectin-9 in the stromal compartment due to their high positivity rate in this subarea." (PMID 35145510, 2021). "The higher expression of FAM3C, LGALS9, ANXA1, SPP1, CD99 and LAMP1 in tumor tissues compared with normal tissues were confirmed by immunohistochemistry in tumors." (PMID 35087839, 2021). "Immune checkpoints expressed in tumor cells, including PD-L1 (CD274), galectin 9 (LGALS9), HVEM (TNFRSF14), exhaust CD8+ T cells and reduce CD8+ T-derived cytotoxicity." (PMID 34685495, 2021).